LEP (leptin)
Diseases named in the same sentence as LEP in open-access papers (continued):
Sharing a sentence is not in itself a finding about the gene and the disease.
Obesity (continued). "Histone modifications in the promoters of leptin, leptin-R and its related satiety regulators will be important to elucidate the regulatory influence of n-3 PUFAs on leptin expression in obesity." (PMID 21609458, 2011). "It is possible that these changes are secondary to the animals' obesity, due perhaps to effects of leptin or other peripheral signals on proNPY and proSAAS expression." (PMID 22164236, 2011). "Mice that lack leptin (ob/ob mice) show hyperphagia (abnormally increased feeding), obesity and insulin resistance, and the administration of leptin to ob/ob mice reverses these changes." (PMID 21960997, 2011). "Serum adipokine levels are known to be dysregulated in obesity, with downregulation of adiponectin and upregulation of leptin and resistin." (PMID 21813022, 2011). "The mechanisms for how saturated fat and sugar-based beverages contribute to human obesity are clearly in rats on an HF choice diet, plasma leptin concentrations and proopiomelanocortin mRNA increased and neuropeptide Y mRNA decreased." (PMID 21235803, 2011). "Deficits in leptin or leptin receptors result in obesity, indicating the importance of the hormone in body mass homeostasis." (PMID 21837282, 2011). "It is particularly interesting to note that chronic leptin administration leads to astrocyte activation suggesting that the potential role of these cells in modulating obesity and neurodegeneration needs to be more extensively investigated in the coming years." (PMID 22013440, 2011). "The elevated plasma leptin level in diet-induced obesity is a predictor of body mass accrual in different species." (PMID 21241467, 2011). "The study of recessive forms of monogenic extreme obesity has been useful in delineating the role of genes from the leptin / melanocortin pathway in human physiology but explains a small percentage of obesity in the population." (PMID 22043164, 2011). "The cross-sectional nature of our research hampered to determine that obesity and sarcopenia affect plasma leptin levels." (PMID 21931785, 2011). "Brain-specific SOCS-3 knockout mice showed elevated leptin sensitivity, were resistant to high fat diet induced obesity and had attenuated insulin resistance." (PMID 21955513, 2011). "In humans though only few cases have been described, while the common form of obesity is presented with high leptin levels, indicating a condition of leptin resistance." (PMID 21949907, 2011). "Leptin, which is increased in obesity, has been found to stimulate inflammatory responses in humans." (PMID 21676245, 2011). "Deuterium studies, for example, have enabled determination of de novo synthesis patterns during early life and in response to high-fat feeding in the Zucker rat model of obesity and leptin resistance." (PMID 21569358, 2011). "Leptin, first discovered in mice and dubbed "the obesity gene", due to the phenotype presented in mutant mice, has subsequently been shown to act as a chemokine, which regulates metabolism." (PMID 22085734, 2011). "The numerous dynamic roles leptin plays in metabolism mean that its initial modelling as an anti-obesity agent has given way to a much more systemic one as an 'integrator of neuroendocrine function'." (PMID 21276254, 2011). "Detrimental effects of leptin are well-documented and collectively support its involvement in obesity-driven vascular dysfunction." (PMID 21533119, 2011). "The expression of leptin is increased in obesity and inhibited by n-3 polyunsaturated fatty acids (n-3 PUFAs), but the underlying molecular mechanisms have not been firmly established." (PMID 21609458, 2011). "A maternal cafeteria or high-fat (HF) diet has been shown to induce obesity, insulin and leptin resistance, hypertension, fatty pancreas disease, hepatic steatosis, and nonalcoholic fatty liver disease in offspring." (PMID 21969822, 2011).
Obesity (continued). "Here, we conducted a cross-sectional study to investigate relationships between plasma leptin levels and sarcopenia and obesity in 782 middle-aged to elderly subjects participating in a medical check-up program in Japan." (PMID 21931785, 2011). "There is now a range of research data published that reveals that leptin is one molecule that is involved in linking obesity to neurodegeneration." (PMID 22013440, 2011). "The association between classical CVD risk phenotypes (hypertension, obesity and lipid status) and the four widely investigated CVD candidate gene polymorphisms is tested: ACE I/D, APOE (ε2, ε3, ε4), eNOS-VNTR and LEP G2548A." (PMID 21244662, 2011). "Leptin KO mice have an obesity phenotype that must be taken into account when interpreting data from leptin KO and WT controls as the leptin KO mice began the experiment weighing almost double that of control weight." (PMID 21464907, 2011). "Defects in eight genes involved in the neuronal differentiation of the paraventricular nucleus and in the leptin/melanocortin pathway, have been shown to lead to human monogenic obesity with hyperphagia as a common feature." (PMID 22043165, 2011). "Leptin levels increase in obesity and leptin has therefore been suggested to belong to the factors explaining the relation between obesity and asthma." (PMID 21615949, 2011). "It is well established that leptin is a satiety signal and thus a decrease in the response to it will decrease satiety, increasing energy intake and thus risking obesity." (PMID 22013440, 2011). "In both women and men, we observed a strong correlation between BMI and leptin level (women: r = 0.71, p<0.001; men: r = 0.94, p<0.001) suggesting a consistency of using BMI and serum leptin level as obesity measures." (PMID 21494606, 2011). "Several studies involving leptin, adiponectin and resistin, have individually shown pleiotropic effects to obesity-related phenotypes with significant heritability estimates." (PMID 21483749, 2011). "It has been shown in animals that leptin administration in the sensitive period after birth can partly reverse the course of development towards obesity." (PMID 21276254, 2011). "It is clear that obesity increases with age and that one of the reasons for this is that the way in which the body responds to leptin changes with age." (PMID 22013440, 2011). "We correlated all three BDI parameters (affective, somatic, and the sum of both components) with the obesity measures (i.e., BMI, serum leptin level, and FLMR)." (PMID 21494606, 2011). "After 15, 30 or 45 weeks, HFD-fed animals presented significant increases in obesity index and serum leptin levels." (PMID 21396114, 2011). "Similar effects were found using a pegylated leptin peptide receptor antagonist (PEG-LPrA2) for inhibition of leptin signaling in lean and diet-obesity-induced mice treated with DMBA [Gonzalez-Perez, Manuscript in preparation]." (PMID 21731759, 2011). "Leptin, a 16-KD polypeptide and the protein product of obesity gene, is synthesized mainly by adipose tissue." (PMID 25587260, 2011). "Leptin, a hormone whose circulating level is increased in obesity, increases system A transport activity through activation of STAT3 and activation of JAK-STAT signalling pathway in human placental villous." (PMID 22144986, 2011). "After adjustment for age and BW, levels of plasma leptin were found to be highest in both men and women among subjects with sarcopenic visceral obesity followed by simple obesity." (PMID 21931785, 2011). "In this study, we report the effect of SRLE on (i) in vivo modulation of genes controlling high fat diet (HFD) induced obesity and (ii) in vitro 3T3L1 pre-adipocyte differentiation and leptin release." (PMID 21845103, 2011). "Most forms of rodent obesity are characterized by increased serum leptin levels and increased leptin mRNA expression in the adipose tissue." (PMID 22007189, 2011).
Obesity (continued). "The decreased activation of leptin signaling and the increase in hypothalamic SOCS3 expression have been clearly related with leptin resistance in obesity." (PMID 21637839, 2011). "In this context, leptin may be one of the mediators responsible for the low-level systemic inflammation that may be present in metabolic syndrome-associated chronic pathologies such as atherosclerosis, which is associated with obesity, especially central obesity." (PMID 20368778, 2010). "Leptin correlated positively with obesity, glucose metabolism, lipid profile, hepatic function and C-reactive protein, and negatively with HDL and Apolipoprotein A-I/B ratio." (PMID 20537155, 2010). "In contrast, leptin levels are elevated in obesity and the current paradigm is that it is released by fat cells in adipose tissue." (PMID 20508843, 2010). "Instead, we conclude that hyperleptinemia is required for the development of leptin resistance in response to diet-induced obesity." (PMID 20613882, 2010). "In our sample, leptin levels were correlated to obesity, glucose metabolism, an 'atherogenic' lipid profile and to liver function." (PMID 20537155, 2010). "These adipocytokines are also BMI dependent in obesity while leptin increases, adiponectin decreases." (PMID 20148112, 2010). "This correlation supports our histological observation that adipocyte hypertrophy was blunted in the HFD-fed OPN KO mice, as plasma leptin levels have been shown to correlate with adipocyte size and fat mass in multiple species models of obesity." (PMID 21103061, 2010). "Obesity is a risk factor for CKD and leptin, the obesity hormone, correlates with body fat mass and markers of renal function." (PMID 20140086, 2010). "A recent study further indicates that mice with disrupted leptin signaling in β cells display hyperinsulinemia, insulin resistance, glucose intolerance, obesity, and reduced fasting blood glucose." (PMID 21113299, 2010). "It is noteworthy that the functional importance of SREBP1, PPARα/γ, NR3H1 and LEP in obesity has been shown in many genetic studies." (PMID 20961460, 2010). "We show that diet-induced obesity mediates the development of osteoarthritis in proportion to increases in adiposity and serum leptin concentration." (PMID 20604941, 2010). "Restoring leptin sensitivity and hypothalamic appetite control presents an exciting new target in obesity management." (PMID 21234320, 2010). "The role of leptin modulating T cell function in humans has been finally defined by clinical studies in specific and rare cases of patients with monogenic obesity." (PMID 20368778, 2010). "The in vivo results implied that compound 1a significantly decreased the body weight, white adipose tissue weight of obesity mice(p < 0.05), reduced leptin and TG in plasma(p < 0.05), elevated HDL-C in serum(p < 0.05)." (PMID 20482839, 2010). "The diet-induced obese mouse is a well characterized system for studying the development leptin resistance and pathogenesis of obesity." (PMID 20613882, 2010). "Recently, deletions in the region p11.2 of the chromosome 16 encompassing the gene SH2B1, which is involved in the leptin and insulin signaling, have been reported in about 0.5% of children with severe early-onset obesity." (PMID 20540750, 2010). "Leptin, the obesity gene (ob) product, participates in the control of body weight by regulating food intake and energy expenditure." (PMID 20592755, 2010). "Under-nutrition severely suppressed plasma insulin and leptin during lactation and diet-induced obesity in adult mice, whereas over-nourished mice were phenotypically indistinguishable from those on a control diet." (PMID 20574519, 2010). "As leptin resistance results in obesity and other metabolic diseases, agents which can re-sensitize the obese to leptin would have great therapeutic value." (PMID 20613882, 2010). "Leptin resistance has been reported to occur in late phases in both rat and human diet-induced obesity." (PMID 20670429, 2010).
Obesity (continued). "Obesity-related metabolic traits included fasting plasma glucose, lipid profiles, leptin, ghrelin, adiponectin and blood pressures." (PMID 20858286, 2010). "On the other hand, increased leptin levels are associated with increased concentrations of other proinflammatory cytokines such as IL-1, IL-6, IL-8, TNFα, and prostaglandin E2, which may provide more specific and selective approaches for pharmacologic intervention in obesity-induced osteoarthritis." (PMID 20604941, 2010). "Leptin is the obesity hormone synthesized mainly by white adipose tissue in humans and its serum level shows strong correlation with body fat mass." (PMID 20140086, 2010). "Identifying the role of adipose-derived proteins in the development and progression of joint disorders has been the aim of increasing investigations, and recent studies propose leptin as a key mediator linking obesity to OA." (PMID 20534145, 2010). "The contribution of leptin resistance to obesity has also been established by the demonstration that hyperleptinemic animals and humans have a blunted response to exogenous leptin." (PMID 20613882, 2010). "The potential effects of leptin in the pathophysiology of cardiovascular complications of obesity remain diverse." (PMID 20847813, 2010). "Over the past decades, several studies have been proposing links among leptin, obesity, diabetes and AD." (PMID 21070531, 2010). "Leptin was identified in 1994 by positional cloning of the ob gene responsible for the development of obesity in ob/ob mice." (PMID 21286276, 2010). "Among the biomarkers that we measured, RBP4 and resistin have previously been shown to be necessary and sufficient to induce insulin resistance and genetic disruption or impaired leptin signaling has been shown to lead to obesity and insulin resistance." (PMID 20633301, 2010). "SOCS-3 is overexpressed in the hypothalamus in various models of leptin resistance such as dietary-induced obesity." (PMID 21286276, 2010). "This study revealed that SREBP1, PPARα/γ, NR3H1 and LEP are key regulatory factors in these pathways and are expressed in zebrafish and mammalian obesity." (PMID 20961460, 2010). "In several obesity models, leptin levels are elevated, reflect adipose mass, and correlate with adipocyte size in humans." (PMID 21103061, 2010). "They used two different obese models, diet-induced obesity (DIO) rats and leptin-deficient ob/ob mice, to show that exercise restores food intake, insulin, and leptin sensitivity to the levels of lean (control) animals." (PMID 20808779, 2010). "Common genetic variants (e.g., SNPs) at the LEPR gene locus have been associated with obesity, hyperinsulinemia, type 2 diabetes mellitus (T2DM), and variations in leptin levels in different populations." (PMID 20624279, 2010). "Hyperleptinaemia is observed frequently in obesity due to leptin resistance, and high levels of IL-1b and other inflammatory mediators are also a common finding in patients with obesity and metabolic syndrome." (PMID 20798765, 2010). "The hyperleptinaemia and implicit leptin resistance characteristics of obesity were abolished by CFE." (PMID 21234320, 2010). "The plasma concentrations of leptin are markedly increased in human obesity and positively correlated to body fat mass." (PMID 20170522, 2010). "This supports prior suggestions that diet-induced obesity results in chronically elevated leptin signaling that cannot be further modulated by additional leptin." (PMID 20613882, 2010). "Other genes involved in the development of obesity, such as leptin and TNF-alpha, have been found to be regulated by epigenetic mechanisms influences by the diet or obesity." (PMID 20534152, 2010). "Leptin is an obesity related mediator, which has been suggested to take part in the regulation of anabolic and catabolic processes within the osteoarthritic joint and to play a role in the pathogenesis of OA." (PMID 19688109, 2009).
Obesity (continued). "Leptin, a possible link between nutritional status and the immune function, is a marker of obesity, participates in pro-inflammatory responses, and is an important growth factor for breast cancer." (PMID 19348684, 2009). "Several studies show that conditions characterized by high levels of leptin (female gender, obesity, menopause) are positively correlated with a higher incidence of breast cancer (BC)." (PMID 19531256, 2009). "Obesity hormone leptin and its receptor (Ob-R) contribute to tumor development by enhancing cell growth and survival." (PMID 19765303, 2009). "AgRPp110α null mice displayed normal energy homeostasis regulation, whereas AgRPp110β null mice were lean, with increased leptin sensitivity and resistance to diet-induced obesity." (PMID 19883613, 2009). "The LHS concept for AIS pathogenesis of girls, views the increased hypothalamic sensitivity to leptin as being at the opposite end of the spectrum to the central leptin resistance of obesity." (PMID 19878575, 2009). "The second avowal could be a relative leptin resistance, due to the fact that leptin seems to downregulate its own receptors, so high leptin levels could possibly reduce the number of leptin receptors and generate a relative leptin resistance which in turn causes obesity." (PMID 19946426, 2009). "We concluded that the increase of serum leptin and adiponectin levels was caused by changes in the WAT such as decreased innervation and vascularization that occurred before onset of obesity." (PMID 19436734, 2009). "Defects in the genes for leptin, leptin receptor, proconvertase 1, pro-opiomelanocortin (POMC) and the melanocortin receptors MC3R and MC4R have been associated with obesity." (PMID 19309531, 2009). "The alarming increase of incidence of obesity in the western countries emphasizes the importance of our findings on leptin-signaling inhibition for reduction of ER+ BC and ER- BC growth." (PMID 19531256, 2009). "Leptin (16 kDa protein), a product of the obesity gene (Ob/Ob), has generated interest among researchers to examine its role in obesity." (PMID 19144201, 2009). "Evidence is mounting to support the idea that leptin is the link between obesity and the higher incidence of a variety of cancers." (PMID 19531256, 2009). "In the present study, we administered a bolus dose of leptin in an attempt to mimic the hyperleptinemic state that accompanies obesity." (PMID 20150963, 2009). "Further, these authors have also shown the repressive effect of leptin on SCD1 expression and therefore, obesity and its associated metabolic changes such as hepatic steatosis in ob/ob mice." (PMID 19519902, 2009). "POMCp110β null mice exhibited central leptin resistance, increased adiposity, and diet-induced obesity." (PMID 19883613, 2009). "However, it has been recently proposed that elevated leptin levels may cause obesity." (PMID 19750222, 2009). "In the setting of diet-induced obesity, serum leptin levels correlate directly with the presence of comorbidities such as cardiovascular disease and liver disease." (PMID 20150963, 2009). "Leptin, the product of the obesity gene (ob) circulates in both free and bound form, and targets neurons including the arcuate nucleus and other nuclei of the hypothalamus." (PMID 19878575, 2009). "In humans, plasma leptin levels, which increase with obesity, are a predictor of heart disease, stroke and cardiovascular mortality in males only." (PMID 19536287, 2009). "Considering the role of leptin in obesity, it is important to identify the modifiable factors of circulating leptin concentrations." (PMID 19144201, 2009). "A key molecule in obesity is leptin, a 16 kDa peptide hormone predominantly produced by white adipose tissue." (PMID 20030801, 2009). "An active role for the adipocyte in energy metabolism was demonstrated with the discovery of leptin and its role in the pathogenesis of obesity." (PMID 19214223, 2009).